IL1B (interleukin 1 beta)
Diseases named in the same sentence as IL1B in open-access papers (continued):
Sharing a sentence is not in itself a finding about the gene and the disease.
Arthritis (continued). "Inflammation further exacerbates this degeneration, as inflammatory cytokines, such as interleukin‐1 beta (IL‐1β), IL‐6, IL‐18 and tumour necrosis factor‐alpha (TNF‐α), promote ECM degradation, highlighting inflammation as a critical driver of arthritis pathogenesis." (PMID 40179133, 2025). "Thus, we inferred that macrophage training induced IL‐1β/NAT10‐mediated ac4C modification on FSP1 mRNA, thereby protecting arthritis synovial FLS from ferroptosis." (PMID 41255239, 2025). "Several studies have demonstrated a correlation between CCR2 and Th17 cells, revealing that mice lacking CCR2 exhibit exacerbated collagen-induced arthritis due to increased Th17 cell activity and elevated levels of IL-17A, IL-6, and IL-1β." (PMID 39903705, 2025). "Furthermore, CA treatment has been shown to decrease the expression of proinflammatory cytokines such as IL-1β, IL-6, TNF-α, IL-23, and IL-17 in various arthritis models." (PMID 39684628, 2024). "In this study, we demonstrated that deZP for pharmacopuncture reduced IL-1β levels and suggested that this effect may be mediated by the NLRP3 inflammasome signal pathway in a gouty arthritis mouse model." (PMID 39861092, 2024). "MOIG treatment inhibited the production of IL-1β, IL-6, IL-8 and TNF-α, and reduced the matrix degradation enzymes expressions of MMP2 and MMP3 in TNF-α-stimulated FLSs, thereby blocking the spread of arthritis to distant joints." (PMID 39444614, 2024). "The zymosan-induced arthritis model is characterized by the release of pro-inflammatory cytokines, such as tumor necrosis factor (TNF), interleukin-18 (IL-18), interleukin-1β (IL-1β), and interleukin-6 (IL-6); synovial joint hypertrophy; and leukocyte recruitment." (PMID 39194751, 2024). "Together, these findings indicate that the release of IL-1β, but not ΙL-6, from phagocytic cells such as macrophages is an important factor in the induction of arthritis in response to infection with A. actinomycetemcomitans." (PMID 39143049, 2024). "The rat model of arthritis also exhibited significant inflammatory response, and peptide BG can significantly inhibit serum pro-inflammatory factor levels, including IgM-RF, CRP, IL-1β, IFN-γ, and TNF-α." (PMID 39669913, 2024). "When the 129/Sv mouse strain, which lacks caspase-11 mRNA expression, was used as a modified CAIA model in the combination with A. actinomycetemcomitans infection, arthritis and IL-1β secretion in the paws were also not observed (data not shown)." (PMID 39143049, 2024). "In addition, the serum levels of IL-1β, TNF-α, and IL-6 showed a significant decrease for rats fed dietary OTMs, which alleviated arthritis symptoms in rats." (PMID 39330501, 2024). "WFR could effectively alleviate the arthritis symptoms of CIA rats; reduce the levels of IL-6, IL-1β, and TNF-α in the peripheral blood of CIA rats; and inhibit the expression of MMP3 and fibronectin." (PMID 38098062, 2023). "The results showed that miR-181a-5p could reduce the release of IL-1β, IL-6, TNF-α and iNOS inflammatory factors in cellular model of arthritis." (PMID 37587519, 2023). "Immunohistochemistry of pro-inflammatory cytokine expression in mouse joint tissues showed that the IL-1β, IL-6, and IL-17 levels were significantly decreased in SMILE Tg mice, thus demonstrating the anti-inflammatory effect of SMILE on arthritis in SMILE Tg mice." (PMID 37143079, 2023). "Interleukin-10 (IL-10), IL-1β, mitogen-activated protein kinase (MAPK), IL-6, matrix metalloproteinase-3 (MMP-3), TNF-α and other targets have been confirmed to play important roles in the treatment of arthritis by CC." (PMID 37637408, 2023).
Arthritis (continued). "Reduction of arthritis scores and spleen and thymus indexes was also observed, as well as the suppression of serum levels of TNF-α, IL-1β, IL-6 and interferon gamma (IFN-γ), which could be attributed to the downregulation of inflammatory mediators." (PMID 37511889, 2023). "As TAS5315 ameliorated the arthritis score in an established mouse CIA model, we further measured whether TAS5315 reduced the levels of TNF-α, IL-1β, and IL-6 in synovial fluid exudates derived from the hind paws." (PMID 36821545, 2023). "IL-1β administration did not restore arthritis suppressed by R69-4, albeit it promoted the migration of immature neutrophils to the periphery, indicating that the reduction of IL-1β is secondary to the protective action of R69-4." (PMID 37741824, 2023). "MC3R knockdown with serum transfer-induced arthritis exacerbated significant bone erosion, high expression of RANKL in the joint, increased time of NF-kB activation, and upregulation of proinflammatory genes [IL-1β, IL-6, and nitric oxide synthase 2 (NOS2)]." (PMID 35874704, 2022). "Since TNF can drive IL-1β secretion via the NLRP3 inflammasome, the role of PAD2 in TNF-induced arthritis may be macrophage-dependent." (PMID 35083342, 2022). "TNF-α, IL-1β, and CXCL1 expression increased after IL-17 injection in an arthritis animal model." (PMID 36248896, 2022). "Taken together, IL-17 is a critical pro-nociceptive cytokine in mBSA-induced arthritis through the promotion of neutrophil migration and production of various pro-inflammatory mediators, such as TNF-α, IL-1β, CXCR1/2 chemokine ligands, MMPs, endothelins, prostaglandins, and sympathetic amines." (PMID 36248896, 2022). "H&E stained sections of wrists confirmed the absence of arthritis in IL-23 EEV injected B6 mice compared to the susceptible B10.RIII strain, and there was no significant induction of Tnf, Il1b, Il17a or Il22 in the wrists of IL-23 EEV injected B6 mice." (PMID 33983951, 2021). "It was reported that the expression of NLRP3, IL-18, and IL-1β in joint synovial fluid was significantly increased in mice with collagen-induced arthritis, and the expression of NLRP3 was correlated with the severity of clinical arthritis." (PMID 33430857, 2021). "In vivo, the effect of PS VII on the weight of the rat, paw swelling, ankle joint diameter, arthritis index, serum inflammatory cytokines (TNF-α, IL-6, and IL-1β), histopathological assessment and apoptosis proteins in the synovial tissues were evaluated in AIA rats." (PMID 34122110, 2021). "In addition, IL-1β promotes PGE2 and collagenase type 2 secretion, which play a major role in the regulation of ECM degradation during arthritis development." (PMID 33567513, 2021). "S100A8/A9 deficiency does not significantly affect inflammation and joint destruction in mice with high IL1β signaling suggesting that S100A8/A9 is not essential for the development of arthritis under these conditions." (PMID 34412663, 2021). "In addition, a high level of IL33 induces the expression of inflammatory cytokines IL1-β, IL6, IL13, and IL17, as well as matrix metalloprotease- (MMP-) 3 and MMP-9 in arthritis." (PMID 34305456, 2021). "Unlike TNF-α, IL-1β is absolutely required for disease development in K/BxN serum transfer arthritis." (PMID 34950033, 2021). "Furthermore, ursolic acid reduced the incidence and severity of CIA-induced arthritis, accompanied by the decreased expression of TNF-α, IL-1β, IL-6, IL-21, and IL-17 in arthritic joints." (PMID 32116720, 2020). "We treated FLS cells with the pro-inflammatory cytokines IL1β and TNFα in order to understand the cellular changes that occur when these FLS are subjected to higher-than-normal levels of these cytokines in vivo, for example, in arthritis." (PMID 32265733, 2020). "Therefore, human chondrocytes (HC) were abstracted and cultured from human cartilage samples and IL-1β, LPS or TNF-α were added to simulate the microenvironment of joint inflammation in vivo." (PMID 32802182, 2020).
Arthritis (continued). "In contrast, in arthritis and some other conditions, IL-33 serves as a pro-inflammatory cytokine and exacerbates inflammation and pain via promoting the production of TNF-α, CXCL1, IL-1β and PGE2 through ST2 in plantar skin tissues 37-39." (PMID 33204337, 2020). "Male mice with higher arthritis activity at 21 weeks had elevated serum levels of multiple cytokines compared to less arthritic females including GM-CSF, IFN-γ, IL-1β, IL-2, IL-12, and IL-17, as well as the growth factor FGF-basic, which correlated with higher arthritic scores." (PMID 33033318, 2020). "Serum-transfer arthritis did not affect concentrations of IL-1β, KC and MIP-1α in the subcutaneous flushing fluid of the hind paws (n = 12–16)." (PMID 31551776, 2019). "To investigate the role of IL-1β in TMJ damage, we assessed whether young mice that lack IL1-RA develop arthritis in the TMJ." (PMID 31067826, 2019). "Non-MHC genes that influence rat PIA arthritis severity include TNFα, IL-1β, IL-6, IL-17, and CCL-2, and joint damaging MMPs." (PMID 29145473, 2017). "The results show that WJHL can significantly alleviate the progression of CIA, reduce ankle swelling, arthritis score, pathological changes, and bone destruction, and increase the level of OPG by inhibiting the levels of TNF-α, IL-1β, IL-6, and IL-17 in the serum of CIA mice." (PMID 28562338, 2017). "Notably, however, similar to what was observed in the hypothalamus, in Charles River rats, mean levels of IL-1β, IL-6, and MCP-1 were highest in rats that developed severe arthritis (Adj/S) whereas in Harlan rats, mean cytokine levels were highest in controls." (PMID 28386080, 2017). "Mice without previously established arthritis showed an upregulation of astrocyte reactivity within the dorsal horn following local spinal overexpression of IL-1β, as well as joint changes indicative of the initial stages of arthritic disease." (PMID 27622932, 2016). "With regards to pro-inflammatory cytokines, IL-1β correlates with and partially precedes the course of clinical arthritis, whereas serum IL-6 and TNFα are not changed during PIA." (PMID 27227821, 2016). "The infiltrated immune cells and synovial fibroblasts secrete various cytokines, like TNF-α, IL-1β, and IL-6, metalloproteinases (MMPs), and chemokines, such as MCP-1, MIP-1, and RANTES, in the inflamed joint tissues and eventually lead to arthritis including inflammation and bone erosion." (PMID 27840652, 2016). "A role of pro-inflammatory cytokines can be discarded because TNF-α and IL-1β levels are not elevated at this time of arthritis." (PMID 26761790, 2016). "In addition, ChondroT decreased the expression of inflammatory enzymes COX-2 and iNOS and reduced the production of inflammatory mediators, such as IL-1β, IL-6, PGE2, and NO, thereby playing important roles in arthritis." (PMID 27411719, 2016). "First, we did not have clinical arthritis samples to evaluate the expression of IL-1β and FGF-2, as well as EPC recruitment in articular cartilage." (PMID 26811540, 2016). "Thus, proinflammatory cytokines (particularly IL-1β, IL-6, and TNF-α) play an important role in arthritis onset, while inhibitors of these cytokines are effective in controlling chronic inflammation." (PMID 27382402, 2016). "Neutrophil influx peaked at 16 hours and being consistent with the elevation of IL-1β, IL-8, and TNF-α release, which could be detected subsequently by 24 h after the induction of arthritis." (PMID 26221174, 2015). "Increased IL-1β and NGF levels in the synovial fluid are symptoms of arthritis." (PMID 26577823, 2015). "IL-6, as well as TNF, IL-1β and PGE2, were reported to up-regulate the RANKL (receptor activator of NF-κB ligand) expression, which was an important prerequisite for osteoclast differentiation and arthritis." (PMID 25602164, 2015). "Since Joyce-Shaikh observed that TNF-α could promote MDL-1 expression in murine arthritis, we examined the role of TNF-α or IL-1β in the regulation of MDL-1 expression." (PMID 24465901, 2014).
Arthritis (continued). "Myeloid cells exhibit excessive proliferation and infiltration into joint tissue of B6 miR-146a−/− mice, have increased phagocytic activity and produce excess cytokines such as IL-1β, IL-6 and CXCL1, leading to inflammation of synovial tissue and arthritis development." (PMID 24967703, 2014). "The present study was designed to identify antiarthritic effects of NHAG in adjuvant-induced arthritis (AIA) and its effects on the circulatory levels of proinflammatory cytokines IL-1β and TNF-α and oxidative stress markers glutathione, nitric oxide, and peroxide." (PMID 23971039, 2013). "Consistent with the results of our in vitro experiments, recombinant IL-12 increased the expression of IFN-γ and IL-1β in the joints of TLR4-/- mice with arthritis, whereas neither recombinant IL-1β nor IFN-γ altered joint IL-12p35 expression levels." (PMID 23036692, 2012). "The results indicated that the beneficial antigouty arthritis effect of EMI may be mediated, at least in part, by inhibiting TNF-α and IL-1β expression in the synovial tissues." (PMID 23304232, 2012). "This beneficial antigouty arthritis effect may be mediated, at least in part, by inhibiting TNF-α and IL-1β mRNA expression and protein levels in the synovial tissues." (PMID 23304232, 2012). "A similar “contralateral effect” (i.e. distal therapeutic effect) has been observed following intra-articular gene transfer of immunosuppressive cytokines, inhibitors of IL-1β and TNF-α, or NF-κB decoy oligonucleotides in rabbit or mouse models of arthritis and DTH." (PMID 21829629, 2011). "The IL-1β and TNF-α were studied by ELISA in the ankle steeps of arthritis model." (PMID 21569552, 2011). "We demonstrated that both TZDs reduced the expression of IL-1β and TNF-α in arthritic synovium, a finding consistent with a recent report of their decrease by the PPAR-γ agonist THR0921 in joints of mice with established collagen-induced arthritis." (PMID 18199331, 2008). "Our results demonstrate up to 125 fold increases in synovial IL1α and IL1β concentrations, approximately 30 fold increases in levels of IL6 and IL10 and a 200–300 fold elevation in synovial concentrations of TNFα during FCA-induced experimental arthritis." (PMID 17567894, 2007). "In addition, at the time point of arthritis onset, a substantial number of the infiltrating inflammatory cells expressed HMGB1 in their cytoplasm, apparently more than cells expressing TNF or IL-1β." (PMID 17397533, 2007). "We have found that the absence of PARP-1 partially reduced the severity of arthritis, likely by the impairment of IL-1β and monocyte chemotactic protein (MCP)-1 transcription in arthritic tissue." (PMID 16356201, 2006). "In arthritis progression, trained macrophages reduce fibroblast‐like synoviocytes’ (FLS) lipid peroxidation, lessening sensitivity to iFSP1‐induced ferroptosis through interleukin‐1 beta (IL‐1β)/N‐acetyltransferase 10 (NAT10)/ferroptosis suppressor protein 1 (FSP1) mRNA ac4C modification." (PMID 41255239, 2025). "In addition, a recent study indicated that blocking TLR4 could effectively attenuate monoiodoacetate-induced arthritis in rats by relieving joint pain and reducing the expression of TNF-α, IL-1β, and matrix metallopeptidase-13 (MMP13)." (PMID 36785752, 2023). "In addition, a very recent paper, using the same CIA model, also suggests that the administration of the PKRs antagonist PC1 improved clinical signs of arthritis, lowered plasma malondialdehyde (MDA) levels, and reduced joint expression of PK2, PKRs, TNFα, IL-1β, CD4, CD8, and NF-kB." (PMID 37759478, 2023). "Here, we show that in arthritis pain, dorsal horn microglia acquire a unique transcriptional profile that is driven by TLR4 upregulation and is enriched in pathways regulating the production and effect of IL-1β, TNF-α and IFN-β, which have been reported to regulate nociception in the K/BxN ST model." (PMID 37349313, 2023).
Arthritis (continued). "Whilst there were some strong associations detected, for example between the IL1B rs16944 and rs1143627 SNPs, between the DPYD rs67376798 SNP and body surface area, and between body surface area and arthritis, none of these associations were evident in 100% of the participants." (PMID 37162533, 2023). "By establishing adjuvant induced arthritis model in rats and ovalbumin induced arthritis model in rabbits, we showed BBR-PPSG could effectively relieve joint swelling, inflammatory cell infiltration, reduce the levels of TNF-α and IL-1β, and maintain the stability of synovial chondrocytes." (PMID 37547331, 2023). "The in vivo results showed that corilagin significantly reduced paw swelling and arthritis score and inhibited joint erosion and the infiltration of inflammatory cells; pro-inflammatory cytokines were also inhibited at the serum level (IL-6, TNF-α, IL-1β, and IL-17)." (PMID 36364420, 2022). "Lymph node cells were isolated from model rats and administered with DAPs, and it was found that the expression levels of IL-1β, IL-2, IL-6, TNF-α and IFN-γ were significantly reduced, while the acceleration of arthritis severity could be attributed to the elevation of these factors." (PMID 36235835, 2022). "As MTX was shown to not be sufficiently effective in decreasing arthritis-stimulated IL-1β gene expression, the use of drugs such as CA capable of increasing the anti-inflammatory action of MTX could represent a promising supplement therapy." (PMID 36296709, 2022). "The study showed that TWG could effectively ameliorate arthritis in CIA rats, such as reducing paw volume and arthritis score, alleviating the pathological damages of joint, and preventing the production of anti-CII autoantibodies and IL-1β cytokine." (PMID 36105231, 2022). "Activation of the P2X7 receptor and NLRP3-dependent IL-1β production by dendritic cells is important for priming of T cells, and this pathway was shown to regulate CD8+ T cell activity in the anti-cancer immune response and Th17 differentiation in arthritis models." (PMID 33995417, 2021). "Because the activation of the NLRP3 inflammasome could induce the overproduction of IL-1β, resulting in inflammation and arthritis, we evaluated the expression of NLRP3, caspase-1 p20 (a functional caspase-1 subunit) and IL-1β in the ankle joint synovial tissue by Western blot." (PMID 34583676, 2021). "Importantly, wedelolactone could abate MSU‐induced IL‐1β production and neutrophils migration into peritoneal cavity, and reduced caspase 1 (p20) and IL‐1β expression in the joint tissue of MSU‐induced arthritis." (PMID 32656909, 2020). "The role of osteoclast formation in arthritis and bone erosion has been well described and it was already reported that HSF played an important role on bone erosion through their ability to secrete a large panel of cytokines such as IL1β, IL-6, M-CSF, GM-CSF and RANKL." (PMID 30074983, 2018). "A lack of MMP-8 causes the aggravation of arthritis through promotion of inflammation by IL-1β and PTX3, inducing the maturation and activation of osteoclasts or enhancement of the inflammatory infiltrate by PROKR2 and IL-1β." (PMID 28445942, 2017). "Interestingly, previous studies reported the presence of AT2R in the synovium of rats with adjuvant-induced arthritis as well as in cultured bovine chondrocytes stimulated with TNF-α or IL-1β pro-inflammatory cytokines, but not in unstimulated cells." (PMID 29038523, 2017). "No other arthritis-related cytokines [IL-1β, TNF, IL-17, interferon-γ, IL-4, CCL5 (also called RANTES, for regulated on activation, normal T cell expressed and secreted) and GM-CSF] could be detected in the serum (data not shown)." (PMID 26081345, 2015).